SCAMP1 (secretory carrier membrane protein 1)
Description:
Functions in post-Golgi recycling pathways. Acts as a recycling carrier to the cell surface.
Synonyms: SCAMP; SCAMP37
Tractability: Antibody: its Gene Ontology location is reachable by antibodies, with high confidence; UniProt predicts a signal peptide or a membrane-spanning region. PROTAC: ubiquitination databases record sites on it; its protein half-life has been measured.
Gene: Protein-coding gene on chromosome 5 (78,360,114 to 78,480,739, forward strand). Ensembl gene ENSG00000085365.
Subcellular location: Golgi apparatus, trans-Golgi network membrane; Recycling endosome membrane
Subcellular location (Human Protein Atlas): Cell Junctions; Nucleoplasm; Vesicles
Pathways (Reactome):
Immune System: Neutrophil degranulation
Gene Ontology:
Molecular function: protein binding; protein domain specific binding
Biological process: protein transport; exocytosis; post-Golgi vesicle-mediated transport; endocytosis
Cellular component: membrane; recycling endosome membrane; trans-Golgi network; clathrin-coated vesicle; plasma membrane; specific granule membrane; trans-Golgi network membrane; cytoplasmic vesicle membrane; Golgi apparatus; synapse; synaptic vesicle membrane; zymogen granule membrane
Genetic constraint (gnomAD): Loss-of-function variants: 5 observed, 12.26 expected, observed/expected ratio (o/e) 0.41, 90% interval 0.21 to 0.86. The upper end of that interval is the gene's LOEUF score, 0.86, which puts it in group 3 of 6, group 1 being the genes least tolerant of losing a copy. Missense variants: 148 observed, 182.05 expected, observed/expected ratio (o/e) 0.81, 90% interval 0.71 to 0.93. Synonymous variants: 66 observed, 66.31 expected, observed/expected ratio (o/e) 1, 90% interval 0.81 to 1.22.
Homologues: Orthologues: macaque SCAMP1 (99% identical), rat Scamp1 (99% identical), mouse Scamp1 (98% identical), pig SCAMP1 (97% identical), dog SCAMP1 (97% identical), guinea pig SCAMP1 (97% identical), rabbit SCAMP1 (93% identical), chimpanzee SCAMP1 (92% identical), tropical clawed frog scamp1 (89% identical), zebrafish scamp1 (79% identical), Drosophila melanogaster Scamp (43% identical), Caenorhabditis elegans scm-1 (39% identical). Paralogues in human: SCAMP3 (54% identical), SCAMP2 (53% identical), SCAMP5 (31% identical), SCAMP4 (29% identical).
Diseases named in the same sentence as SCAMP1 in open-access papers:
SCAMP1 is named in the same sentence as 26 diseases in open-access papers, as found by Europe PMC text mining. Sharing a sentence is not in itself a finding about the gene and the disease. The quoted sentences say what the papers report.
breast carcinoma (7 papers, 2018 to 2023). "In summary, we provide evidence of the cooperative roles of MTSS1 and SCAMP1 in preventing HER2+/ER−/PR− breast cancer invasion and we show that the loss of Mtss1 and Scamp1 results in a more aggressive cancer cell phenotype." (PMID 29497041, 2018). "Furthermore, we determined the translational importance of this proposal in a clinical setting by showing that loss of MTSS1 and SCAMP1 expression are specifically associated with a worse prognosis in HER2+/ER−/PR− breast cancer." (PMID 29497041, 2018). "When it comes to both estrogen receptor-positive and HER2 breast cancers, there is an interesting dynamic at play involving SCAMP1 (Secretory Carrier-Associated Membrane Protein 1)." (PMID 37762375, 2023). "In breast cancer cells, SCAMP1 prevented cell invasion via cooperation of MTSS1 (metastasis suppressor protein 1) in breast cancer." (PMID 35992869, 2022). "Loss of SCAMP1 and MTSS1 in breast cancer tissues associated with poor disease-specific survival in HER2+ breast cancer patients." (PMID 35992869, 2022). "Emerging studies suggest that the dysregulation of SCAMP1 is related to the occurrence and progression of various tumors, including pancreatic cancer, gallbladder cancer, cervical cancer and breast cancer." (PMID 33493138, 2021). "SCAMP1-regulated MTSS1 prevents a more aggressive cancer cell phenotype and its loss is responsible for reduced survival in patients with HER2+/ER−/PR− breast cancer." (PMID 29497041, 2018). "Identification of MTSS1 and SCAMP1 as key regulators of HER2+ cancer progression by artificial neural network (ANN)-based integrative data mining HER2+ breast cancers are among the most aggressive type of breast cancer." (PMID 29497041, 2018). "This was clinically tested in HER2 breast cancer tissue and shown that loss of MTSS1 and SCAMP1 correlates with reduced disease-specific survival." (PMID 29497041, 2018). "To investigate the expression of endogenous MTSS1 and SCAMP1 in breast cancer cell lines, we performed immunoblotting (IB) using whole-cell extracts from SkBr3 and MDA-MB-453 (HER2+/ER−/PR−) and BT-474 (HER2+/ER+/PR+) human breast cancer cells." (PMID 29497041, 2018). "Moreover, we reveal the dual role of MTSS1 and SCAMP1 in preventing HER2+ breast cancer progression." (PMID 29497041, 2018). "Taken together, these results confirm our hypothesis of synergistic interaction between MTSS1-mediated and SCAMP1-mediated cellular pathways in preventing HER2+/ER−/PR− breast cancer invasion." (PMID 29497041, 2018). "Likewise, restoring SCAMP1 expression in HER2+/ER−/PR− breast cancer cell lines also promoted cell–cell adhesion and prevented cell invasion." (PMID 29497041, 2018). "To better understand the role of MTSS1 and SCAMP1 in tumour progression, we investigated their influence on cell migration and invasion using HER2+ breast cancer cell lines, and MTSS1-expressing and SCAMP1-expressing constructs." (PMID 29497041, 2018). "An increased cell migration of BT-474 breast cancer cells was also observed following combined MTSS1 and SCAMP1 knockdowns, and when compared to the control or when MTSS1 or SCAMP1 were individually knocked down." (PMID 29497041, 2018). "To determine whether MTSS1 and SCAMP1 interact, we performed a proximity ligation assay (PLA) and immunoprecipitation (IP) experiment using whole-cell extracts from the BT-474 breast cancer cell line." (PMID 29497041, 2018). "Indeed, we found that SCAMP1 expression correlated with Mtss1 expression in tumours with the HER2+/ER−/PR− phenotype and its expression was decreased similarly to MTSS1 in the HER2+/ER−/PR− breast cancer class." (PMID 29497041, 2018). "To investigate whether this hypothesis is translated in the clinical setting, we verified the presence and the expression of MTSS1, SCAMP1 and SERPIN B13 in a cohort of breast cancer patients by immunohistochemistry staining, using specific antibodies to these proteins." (PMID 29497041, 2018).
breast carcinoma (continued). "As a transcript of SCAMP1 gene, lncRNA Homo sapiens secretory carrier-associated membrane protein 1, transcript variant 2 (SCAMP1-TV2; GenBank, NR_110885.1) cannot be translated into protein, and the expression and effects of SCAMP1-TV2 in breast cancer have not been reported." (PMID 32670859, 2020). "On the basis of this background, we hypothesised that the vesicle carrier protein SCAMP1 is involved in stabilising MTSS1 protein trafficking that promotes MTSS1 anti-invasive and anti-metastatic functions by endorsing cell–cell adhesion in HER2+ breast cancer." (PMID 29497041, 2018).
glioma (7 papers, 2019 to 2023). A benign or malignant brain and spinal cord tumor that arises from glial cells (astrocytes, oligodendrocytes, ependymal cells). "For the first time, these results revealed that SCAMP1 acted as a lncRNA conducted carcinogenic functions in glioma cells, whereas the underlying mechanisms need to be further clarified." (PMID 31207033, 2019). "In addition, NLRC5 expression was shown to be downmodulated by the lncRNA SCAMP1 (Secretory carrier-associated membrane protein 1) in gliomas." (PMID 37108368, 2023). "LMX1A was found to be a downstream target of miR-499a-5p and participated in lncRNA SCAMP1-induced oncogenesis in glioma." (PMID 35992869, 2022). "SCAMP1 also suppresses the malignant proliferation of glioma cells through the miR-499a-5p/LMX1A/NLRC5 axis, highlighting SCAMP1 as an oncogene." (PMID 33493138, 2021). "Knockdown of SCAMP1 significantly inhibited the proliferation ability while facilitated apoptosis of glioma cells compared with the sh‐NC group." (PMID 31207033, 2019). "The present study demonstrated that LncRNA secretory carrier membrane protein 1 (SCAMP1) was up‐regulated and functioned as an oncogene in glioma cells." (PMID 31207033, 2019). "In brief, SCAMP1 played an oncogenic role in glioma cells via repressing miR‐499a‐5p expression, however, the deeper mechanisms of miR‐499a‐5p‐induced tumour‐suppressive effects were still unclear." (PMID 31207033, 2019). "Conversely, the SCAMP1 expression in glioma cells transfected with miR‐499a‐5p agomir was remarkably decreased." (PMID 31207033, 2019). "Results showed that down‐regulation of miR‐499a‐5p expression dramatically reversed the suppressive effect on LMX1A by SCAMP1 knockdown in glioma cells." (PMID 31207033, 2019). "In summary, our study revealed that LncRNA SCAMP1 plays an oncogenic role while miR‐499a‐5p exerts tumour‐suppressive functions in glioma cells." (PMID 31207033, 2019). "Further experiments showed that miR‐499a‐5p expression was negatively correlated with SCAMP1 expression and SCAMP1 knockdown obviously up‐regulated miR‐499a‐5p in glioma." (PMID 31207033, 2019). "In addition, upregulation of the lncRNA secretory carrier membrane protein 1 (SCAMP1), which functions as an oncogene in glioma cells, significantly promotes glioma cell proliferation, migration, and invasion and inhibits apoptosis." (PMID 34220868, 2021). "Our data showed LncRNA SCAMP1 was up‐regulated in glioma tissues and cell lines and inhibition of SCAMP1 expression significantly suppressed the cell proliferation, migration and invasion, moreover, facilitated apoptosis of glioma cells." (PMID 31207033, 2019). "For deeply investigating the functions of SCAMP1 in glioma, we up‐regulated and down‐regulated the expression of SCAMP1 in glioma cells, then the effects on malignant biological behaviours were detected by CCK‐8 assay, flow cytometry analysis and transwell assay." (PMID 31207033, 2019). "In this study, we confirmed that SCAMP1 was overexpressed in glioma tissues and cell lines." (PMID 31207033, 2019). "miRNAs microarray analysis was employed to identify that miR‐499a‐5p was remarkably up‐regulated in glioma cells when SCAMP1 knockdown, implying miR‐499a‐5p may participate in SCAMP1‐induced modulation on glioma cells." (PMID 31207033, 2019). "Data above suggested that SCAMP1 acted as an oncogene in glioma cells." (PMID 31207033, 2019). "Hence the LMX1A expression of glioma cells altered SCAMP1 and miR‐499a‐5p expression was firstly detected." (PMID 31207033, 2019). "Furthermore, Kaplan‐Meier survival analyses and log‐rank test in 31 glioma patients suggested that higher SCAMP1 expression indicated poorer overall survival." (PMID 31207033, 2019). "In addition, SCAMP1 knockdown significantly inhibited the malignant biological behaviours of glioma cells." (PMID 31207033, 2019). "SCAMP1 could increase LMX1A by negative regulating miR‐499a‐5p expression in glioma cells." (PMID 31207033, 2019).
glioma (continued). "Hence, the biological effects of SCAMP1 as a lncRNA on glioma should be penetratingly investigated." (PMID 31207033, 2019). "This suggests that NLRC5 plays a regulatory role in the development of glioma and is related to IFN signaling and the SCAMP1/miR-499a-5p/LMX1A/NLRC5 pathway." (PMID 34220868, 2021). "The expression levels of SCAMP1 in NBTs, glioma tissues, NHA and glioma cell lines were detected by qRT‐PCR." (PMID 31207033, 2019). "In conclusion, the SCAMP1/miR‐499a‐5p/LMX1A/NLRC5 axis serves as a critical regulator of tumourigenesis and progression of glioma, providing a novel therapeutic strategy for glioma treatment." (PMID 31207033, 2019). "In our study, the expression levels of SCAMP1, miR‐499a‐5p, LMX1A and NLRC5 were investigated in glioma tissues and cell lines, meanwhile, the effects on regulating malignant progression of glioma and cross‐talk among SCAMP1, miR‐499a‐5p, LMX1A and NLRC5 were completely clarified." (PMID 31207033, 2019). "The previous results uncovered that LMX1A exerted cancerogenic functions in glioma cells, however whether LMX1A was involved in SCAMP1 and miR‐499a‐5p regulatory malignant progression of glioma cells remains blurry." (PMID 31207033, 2019). "Hence, down‐regulation of SCAMP1 remarkably reduced the expression level of LMX1A, indicating that LMX1A participated in miR‐499a‐5p‐induced tumour‐suppressive effects on glioma cells." (PMID 31207033, 2019). "In conclusion, our study clarifies that SCAMP1/miR‐499a‐5p/LMX1A/NLRC5 axis plays a critical role in modulating malignant progression of glioma cells, which provide a novel therapeutic strategy for glioma treatment." (PMID 31207033, 2019). "Consequently, the molecular mechanism revealed that knockdown of SCAMP1 increased miR‐499a‐5p expression, which hindered the expression of LMX1A and NLRC5, further led to carcinostatic effects on glioma cells by repressing the activity of Wnt/β‐catenin signalling pathway." (PMID 31207033, 2019).
pancreatic cancer (5 papers, 2011 to 2023). "LncRNA SCAMP1 was reported to be significantly upregulated in pancreatic cancer tissues compared with normal tissues." (PMID 35992869, 2022). "In pancreatic cancer tissues, SCAMP1 was remarkable upregulated in tissues with lymph node metastasis compared with tissues without metastasis." (PMID 35992869, 2022). "Silencing of SCAMP1 by siRNA transfection led to a marked suppression in invasion and migration in pancreatic cancer cells and gallbladder cancer cells." (PMID 35992869, 2022). "SCAMP1 expression was correlated with the patient clinicopathological features in pancreatic cancer, including TNM stage, neural invasion, poor prognosis." (PMID 35992869, 2022). "By combining expression analysis and survival analysis for these lncRNAs in pancreatic cancer using TCGA data, only 4 lncRNAs (SCAMP1, HCP5, MAL2, LINC00511) were defined as the key lncRNAs." (PMID 31061236, 2019). "Pancreatic cancer patients with unfavorable survival often had higher expression of lncRNA SCAMP1." (PMID 35992869, 2022). "Knockdown of SCAMP1 reduced the activity of vascular endothelial growth factor (VEGF) in gallbladder cancer and pancreatic cancer." (PMID 35992869, 2022). "Only 10 (SCAMP1, EMG1, HCP5, TUG1, MAL2, H19, LINC00511, RP11-311C24.1, RP11-400F19.6 and CTC-459F4.3) out of 90 lncRNAs were significantly upregulated in pancreatic cancer samples when compared with normal controls." (PMID 31061236, 2019). "The mRNA-miRNA-lncRNA regulatory network predicted that lncRNA SCAMP1 could bind to miR-132-3p and MMP9 in pancreatic cancer cells." (PMID 35992869, 2022). "SCAMP1 is differentially expressed in normal vs. tumor tissue in patients with cervical cancer and pancreatic cancer lacking lymph node metastasis." (PMID 33493138, 2021). "The expression of LZIC, FXR, SCAMP1, and SULT1E1 was significantly higher in pancreatic cancer tissues with LN metastasis than in pancreatic cancer tissues without LN metastasis." (PMID 21364590, 2011). "In summary, microarrays together with real-time PCR validation results clearly show that the expression of LZIC, FXR, SCAMP1, and SULT1E1 were confirmed to be significantly higher in pancreatic cancer tissues with LN metastasis than in pancreatic cancer tissues without LN metastasis." (PMID 21364590, 2011).
gallbladder cancer (3 papers, 2017 to 2022). "We previously demonstrated that SCAMP1 silencing inhibits the metastatic phenotypes of human pancreatic and gallbladder cancer cells." (PMID 33493138, 2021). "Moreover, SCAMP1 was also reported to be highly expressed in both human pancreatic and gallbladder cancer cells." (PMID 29312605, 2017). "And SCAMP1 could be regarded as the potential targeted gene for treatment of pancreatic and gallbladder cancer." (PMID 29312605, 2017). "It was shown that down regulation of SCAMP1 inhibited vascular endothelial growth factor (VEGF) activity in both human pancreatic and gallbladder cancer cell lines." (PMID 29312605, 2017).
lymph node metastasis (2 papers, 2021 to 2024). "Herein, we examined the expression of SCAMP1 in gastric cancer (GC) tissues and found that it was aberrantly increased and positively correlated with tumor size and lymph node metastasis." (PMID 39308691, 2024).
ovarian carcinoma (2 papers, 2012 to 2022). A malignant neoplasm originating from the surface ovarian epithelium. "For example, lncRNA SCAMP1 was remarkable elevated in ovarian cancer cells and tissues, and overexpression of lncRNA SCAMP1 induced angiogenesis and invasion." (PMID 35992869, 2022). "Moreover, lncRNA SCAMP1 can bind with miR-137 and upregulate the expression of CXCL12 (C-X-C motif chemokine ligand 12) in ovarian cancer cells." (PMID 35992869, 2022).
pancreatic adenocarcinoma (2 papers, 2021 to 2024). "A previous study showed that high SCAMP1 expression was indicative of poor prognosis in patients with pancreatic adenocarcinoma 13, which prompted us to perform a prognostic analysis of SCAMP1 in patients with GC." (PMID 39308691, 2024). "Chi-Square tests were used to investigate SCAMP1, 5 expression in adjacent normal and pancreatic adenocarcinoma (p<0.0001)." (PMID 33493138, 2021).
renal cell carcinoma (2 papers, 2020 to 2022). "Knockdown of lncRNA SCAMP1 induced apoptosis and reduced cell viability in renal cell carcinoma cells after H2O2 treatment." (PMID 35992869, 2022). "The exposure of renal cell carcinoma cells to H2O2 to induce oxidative stress leads to a downregulation of the lncRNA ‘secretory carrier membrane protein 1′ (SCAMP1) and to apoptosis of the cells." (PMID 32492865, 2020). "Furthermore, lncRNA SCAMP1 also affected autophagy and miR-429-mediated tumorigenesis in renal cell carcinoma." (PMID 35992869, 2022). "LncRNA SCAMP1 has been reported to regulate ZEB1/JUN axis in renal cell carcinoma." (PMID 35992869, 2022). "In renal cell carcinoma specimens, the expression of lncRNA SCAMP1 was highly elevated." (PMID 35992869, 2022). "Therefore, lncRNA SCAMP1 enhanced progression of renal cell carcinoma via regulation of autophagy and miR-429/ZEB1/JUN axis under oxidative stress." (PMID 35992869, 2022). "Moreover, miR-429 was found to interact with lncRNA SCAMP1 in renal cell carcinoma cells." (PMID 35992869, 2022).
gastritis (1 paper, 2023). Inflammation of the stomach. "In this study, we screened 11 important lncRNAs (AFAP1-AS1, MIR155HG, LINC00472, and FAM201A) and mRNAs (CASP10, SLC26A2, TRIB1, BMP2K, SCAMP1, TNKS1BP1, and MBOAT2) according to the gene expression profiles of gastric epithelial tissues in different stages of Hp infection-induced gastritis." (PMID 37249580, 2023).
hepatoma (1 paper, 2022). "Taken together, the effect of SCAMP1 on viral transcription is by the specific transcriptional inhibition of HBV EnhI/Xp, SP1, and SP2 promoters, rather than from a general or global effect on human hepatoma cells." (PMID 35216324, 2022).